UBE3B (ubiquitin protein ligase E3B)
Description:
E3 ubiquitin-protein ligase which accepts ubiquitin from an E2 ubiquitin-conjugating enzyme in the form of a thioester and then directly transfers the ubiquitin to targeted substrates. Ubiquitinates BCKDK and targets it for degradation, thereby regulating various metabolic processes (By similarity). Involved in the positive regulation of neurite branching in hippocampal neurons and the control of neuronal spine number and morphology, through the ubiquitination of PPP3CC (By similarity).
Synonyms: BPIDS; KOS
Tractability: PROTAC: ubiquitination databases record sites on it; its protein half-life has been measured.
Gene: Protein-coding gene on chromosome 12 (109,477,402 to 109,536,705, forward strand). Ensembl gene ENSG00000151148.
Subcellular location: Postsynaptic density
Subcellular location (Human Protein Atlas): Nuclear speckles; Mitochondria
Pathways (Reactome):
Immune System: Antigen processing: Ubiquitination & Proteasome degradation
Gene Ontology:
Molecular function: protein binding; ubiquitin protein ligase activity; ubiquitin-protein transferase activity
Biological process: protein polyubiquitination; ubiquitin-dependent protein catabolic process; protein ubiquitination; regulation of postsynapse assembly
Cellular component: mitochondrion; postsynaptic density; glutamatergic synapse; postsynapse
Genetic constraint (gnomAD): Loss-of-function variants: 70 observed, 126.48 expected, observed/expected ratio (o/e) 0.55, 90% interval 0.46 to 0.68. The upper end of that interval is the gene's LOEUF score, 0.68, which puts it in group 2 of 6, group 1 being the genes least tolerant of losing a copy. Missense variants: 1,113 observed, 1,327.7 expected, observed/expected ratio (o/e) 0.84, 90% interval 0.8 to 0.88. Synonymous variants: 462 observed, 506.43 expected, observed/expected ratio (o/e) 0.91, 90% interval 0.85 to 0.99.
Gene-disease validity (ClinGen):
ClinGen rates the evidence that UBE3B causes each of these diseases.
oculocerebrofacial syndrome, Kaufman type (autosomal recessive): Definitive.
Homologues: Orthologues: chimpanzee UBE3B (99% identical), macaque UBE3B (99% identical), pig UBE3B (96% identical), dog UBE3B (96% identical), rabbit UBE3B (95% identical), guinea pig UBE3B (95% identical), mouse Ube3b (92% identical), rat Ube3b (92% identical), tropical clawed frog ube3b (84% identical), zebrafish ube3b (82% identical), Drosophila melanogaster CG5087 (48% identical), Caenorhabditis elegans oxi-1 (38% identical). Paralogues in human: UBE3C (28% identical), HECW2 (20% identical), HECW1 (20% identical), HUWE1 (20% identical), NEDD4 (17% identical), WWP1 (17% identical), ITCH (17% identical), NEDD4L (16% identical), WWP2 (16% identical), SMURF2 (16% identical), HECTD4 (15% identical), HACE1 (15% identical), and 12 more.